MX2 (MX dynamin like GTPase 2)
Description:
Interferon-induced dynamin-like GTPase with potent antiviral activity against human immunodeficiency virus type 1 (HIV-1). Acts by targeting the viral capsid and affects the nuclear uptake and/or stability of the HIV-1 replication complex and the subsequent chromosomal integration of the proviral DNA. Exhibits antiviral activity also against simian immunodeficiency virus (SIV-mnd). May play a role in regulating nucleocytoplasmic transport and cell-cycle progression.
Synonyms: MXB
Tractability: Antibody: its Gene Ontology location is reachable by antibodies, with medium confidence. PROTAC: ubiquitination databases record sites on it; its protein half-life has been measured.
Gene: Protein-coding gene on chromosome 21 (41,361,957 to 41,409,417, forward strand). Ensembl gene ENSG00000183486.
Subcellular location: Cytoplasm; Nucleus; Nucleus, nuclear pore complex
Pathways (Reactome):
Immune System: ISG15 antiviral mechanism; Interferon alpha/beta signaling
Gene Ontology:
Molecular function: GTP binding; protein binding; GTPase activity; microtubule binding
Biological process: defense response to virus; regulation of cell cycle; regulation of nucleocytoplasmic transport; response to interferon-alpha; response to virus; defense response; synaptic vesicle budding from presynaptic endocytic zone membrane
Cellular component: nuclear pore; cytoplasm; cytosol; nucleus; plasma membrane; synapse; nuclear envelope; presynapse
Genetic constraint (gnomAD): Loss-of-function variants: 51 observed, 78.18 expected, observed/expected ratio (o/e) 0.65, 90% interval 0.52 to 0.82. The upper end of that interval is the gene's LOEUF score, 0.82, which puts it in group 3 of 6, group 1 being the genes least tolerant of losing a copy. Missense variants: 832 observed, 954.52 expected, observed/expected ratio (o/e) 0.87, 90% interval 0.82 to 0.92. Synonymous variants: 369 observed, 357.64 expected, observed/expected ratio (o/e) 1.03, 90% interval 0.95 to 1.12.
Homologues: Orthologues: chimpanzee MX1 (99% identical), macaque MX2 (92% identical), dog MX2 (74% identical), pig MX2 (69% identical), Drosophila melanogaster shi (25% identical), Caenorhabditis elegans dyn-1 (25% identical). Paralogues in human: MX1 (56% identical), DNM3 (26% identical), DNM1 (26% identical), DNM2 (26% identical), DNM1L (25% identical), OPA1 (22% identical).
Diseases named in the same sentence as MX2 in open-access papers:
MX2 is named in the same sentence as 97 diseases in open-access papers, as found by Europe PMC text mining. Sharing a sentence is not in itself a finding about the gene and the disease. The quoted sentences say what the papers report.
viral infection (66 papers, 2006 to 2025). "MX dynamin‐like GTPase 2 (MX2) encodes a protein that has been recognized in the immune defense against virus infection and in the response to interferon α." (PMID 35355298, 2022). "SiRNA-mediated silencing of MX2 reduced the suppression of virus infection caused by IFNα by ~50% when compared with the CTRL siRNA." (PMID 30496303, 2018). "Meanwhile, the transcriptional levels of interferon-stimulated genes (ISGs) such as ISG15, ISG20, OAS1, OAS2, MX1, and MX2 were significantly up-regulated, and these ISGs play a crucial role in resisting viral infection." (PMID 41153955, 2025). "We find that this domain affects viral infection, nucleoporin requirements, MX2 sensitivity, and integration targeting in a CA-specific manner, providing detailed insights into how RANBP2 contributes to HIV-1 infection." (PMID 39853118, 2025). "The HIV-1 capsid (CA) is the major viral determinant for sensitivity to MX2, and complex interactions between MX2, CA, nucleoporins (Nups), cyclophilin A (CypA), and other cellular proteins influence the outcome of viral infection." (PMID 38512975, 2024). "The increased detection of MX2, an interferon-stimulated gene induced by Type I interferons in response to viral infections, mainly HIV-1, was only found in piglet muscle tissue." (PMID 35566276, 2022). "By constructing a PPI network, 15 hub target genes were obtained, and the top 3 node degrees were MX2 (down-regulated in MS), DDX60 (down-regulated in MS) and IRF7 (down-regulated in MS), all of which were associated with the viral infection." (PMID 36341423, 2022). "The mechanisms by which Mx2 affects viral infection mainly rely on the guanosine triphosphatases (GTPases) domain, which is associated with targeting the viral capsid and hindering uncoating/nuclear accumulation of viral genome DNA17,29,30." (PMID 34707174, 2021). "While the impact of Mx2 expression on cellular immune response against viral infection is barely mentioned." (PMID 34707174, 2021). "Although we have shown that Mx2 correlates with limited oHSV-1 multiplication in A172 cells, it is important to explore the mechanism of how Mx2 affects viral infection." (PMID 34707174, 2021). "Based on our data we formally cannot distinguish between both alternatives, although a number of earlier reports exclude a direct stimulation of Mx2 by virus infection." (PMID 33137201, 2020). "We find that HIV-1 CA sequence, target cell-type, cell-cycle, CypA, and multiple Nups functionally interact in complex ways to affect the efficiency of viral infection and the antiviral activity of MX2." (PMID 30084827, 2018). "Additional indirect evidence includes the increased expression of genes such as MX2 that is induced during viral infections by IFN-αβ." (PMID 22096503, 2011). "The group includes genes of the innate response to viral infection that are interferon induced (ISGs): examples of this group include the six 2′-5′-oligoadenylate synthetase (Oas) genes, the Mx1 and Mx2 genes, Irf7 and Pkr." (PMID 18927629, 2008). "The relevance of EN2-induced MX2 expression in cells adjacent to the tumor is unclear, although it could be advantageous for the tumor to prevent viral infection of stromal cells that would otherwise generate a localized immune response." (PMID 30914795, 2019). "Thus, the targets and mechanisms underlying inhibition of viral infection by MX1 and MX2 are quite distinct." (PMID 30084827, 2018). "Mx2 is one out of many IFN-induced proteins that protect cells against viral infection." (PMID 28659914, 2017). "This Hypothesis is supported by the upregulation of MX1 and MX2, both of which are up-regulated in response to viral infection." (PMID 20707927, 2010).
viral infection (continued). "Finally, while anti-viral specificity of MX1 is largely determined by a disordered loop (L4) in the stalk domain, antiviral specificity of MX2 is determined by the N-terminal domain (NTD), indicating that the mechanisms underlying inhibition of viral infection by MX1 and MX2 are distinct." (PMID 38512975, 2024). "However, we cannot exclude that virus infection leads to a direct Mx2 induction through IRF3 activation implying that the converter system may be triggered independently of IFNAR signaling." (PMID 33137201, 2020). "Therefore, we surmised that the cellular localization of equine Mx2 might be altered following virus infection." (PMID 29743377, 2018). "The induction of OAS1, OAS2, and OASL, which, as main sensors for viral infections, explains the induction of numerous interferon-induced proteins (e.g., IFIT1, IFIT2, IFI44, MX1, MX2)." (PMID 39062793, 2024). "Elevated levels of MX2 have been identified in individuals with SARS-CoV-2, and other viral infections." (PMID 37255317, 2023). "Especially, many ISGs were modified with ubiquitin during viral infections such as MX1, MX2, OAS2, ISG15, and ISG20, which has rarely been reported before." (PMID 36071039, 2022). "We validated the relevance of MX1, MX2, ISG15, and OAS1 in the context of viral infections in cell cultures in vitro and in a pre-clinical model of Coronavirus infection." (PMID 36298734, 2022). "These transcriptional signatures of acute viral infection resolved in most cell types by day 7 after infection, with the exception of lingering MX1/MX2 expression in some populations of macrophages and DCs." (PMID 35653196, 2022). "MX2 is a cytokine induced by interferon IFN-α, which resists viral infection by inhibiting the accumulation of viral nuclear DNA." (PMID 34880865, 2021). "ISGs are effector molecules that mediate cellular innate immune responses to viral infections, including PKR, OAS1, Mx1, and Mx2." (PMID 32133381, 2020). "We extended our analysis to a range of ISGs that have previously been identified as being regulated directly by virus infection in an IFN-independent manner i.e., IFIT1, IFIT2, IFIT3, ISG15, CXCL10, Mx1 and Mx2." (PMID 30871003, 2019). "Among these, the expression of Mx1, Mx2, TRIM22, WARS, ISG15, ISG20, UBA7, DDX58, and OAS1-3 were up-regulated, representing an increased innate immune response against viral infections." (PMID 25883591, 2015). "This study provides provocative insight into the function of these RFs in counteracting early virus infection in the mucosa and is the first report of the SCHL11 and Mx2 response to primary SIV infection and their relationship to the other ISGs in vivo." (PMID 24884551, 2014). "Overall, the observed increase in MX2 and IFIT1 expression with BYBG may improve the trained innate immune response to future viral infection." (PMID 39846553, 2025). "Including outliers yielded additional immune function–related genes, including those responsive to viral infection (CCL20, CXCR5, MX2), suggesting that these 2 samples may represent a more highly inflammatory state." (PMID 41212059, 2025). "The top 4 were “Cell matrix adhesion and organization” (COL6A1, COL6A2, COL18A1, JAM2, ADAMTS5 and POFUT2), “Immune/virus infection response” (MX1 and MX2), “Histone modification and chromatin remodeling” (NRIP1) and “Glycerolipid and lipid metabolism” (AGPAT3)." (PMID 38095646, 2023). "II) “Immune/virus infection regulation”, including MX1 and MX2." (PMID 38095646, 2023). "In humans, MX1 and MX2 (also known as MxA and MxB respectively) are, in contrast to many other interferon-induced proteins, strictly induced by IFN and found to be increased in the plasma of patients suffering from viral infections." (PMID 34079538, 2021). "The direct impact of Schlafen 11, SAMHD1, and Mx2 in controlling virus infection/disease in vivo in either system has not yet been shown." (PMID 24884551, 2014).
viral infection (continued). "MX1, MX2, and OAS family members OAS1, OAS2, OAS3 mediate resistance to virus infection." (PMID 18648529, 2008). "Since up-regulated MX2 gene was observed in MS twins treated with IFN-β, its up-regulation may be explained by this treatment or alternatively by unknown virus infection." (PMID 16504146, 2006). "Wild-type (WT) or CA-mutant HIV-1-GFP reporter virus infection of dividing or non-dividing (aphidicolin treated) HeLa or HT1080 cells expressing doxycycline-inducible MX2 in the presence (white bars) or absence (black bars) of pretreatment with doxycycline (Dox) and the presence or absence of CsA." (PMID 30084827, 2018).
HIV-1 infection (59 papers, 2014 to 2025). The type species of lentivirus and the etiologic agent of acquired immunodeficiency syndrome (AIDS). "We observed defective infection for cells expressing the cytoplasmic localizing CPSF6-NLS mutants, while cells expressing the NP and MX2 NLS variants again supported reduced levels of HIV-1 infection." (PMID 38979149, 2024). "For instance, the NR_003508-associated gene is MX2, which is an interferon-induced inhibitor of HIV-1 infection." (PMID 35631053, 2022). "Because the effects of CA mutation on HIV-1 infection and MX2 sensitivity varied with cell-type, we next investigated the effects of Nup depletion on selected HIV-1 CA mutants." (PMID 30084827, 2018). "Additionally, MX1 is found to be associated with HIV total DNA and MX2 can be involved in the innate immune response to HIV-1 infection." (PMID 41226717, 2025). "Because the effect of CsA on HIV-1 infection was modified by CA mutations in different ways depending on the identity of the target cell, we tested whether Nup depletion altered the effects of CsA and/or MX2 on HIV-1 CA mutants." (PMID 30084827, 2018). "We have used precise gene editing to assess the role of the cyclophilin domain of RANBP2 in HIV-1 infection and MX2 activity." (PMID 39853118, 2025). "Sensitivity of HIV-1 to MX2 activity is affected by complex interactions between CA and cellular proteins involved in the early stages of HIV-1 infection (reviewed in reference 39), including RANBP2." (PMID 39853118, 2025). "Using this approach, we investigated the function of the Cyp homology domain of the cytoplasmic filament Nup RANBP2 in HIV-1 infection and MX2 activity." (PMID 39853118, 2025). "Modern gene-editing technology now provides the opportunity to directly test the role of individual Nup domains in HIV-1 infection and MX2 activity by generating cells expressing Nups from their endogenous loci, but with specific domains deleted." (PMID 39853118, 2025). "We previously demonstrated that CypAD66N and CypAD66N/R69H do not bind HIV-1 CA and that cells expressing these mutant CypA proteins phenocopy CsA-treated and CypA−/− cells with regard to HIV-1 infection and MX2 sensitivity." (PMID 39853118, 2025). "MX2 inhibits HIV-1 infection prior to chromosomal DNA integration, but after the completion of reverse transcription, and current models suggest that it acts by preventing nuclear import of the preintegration complex." (PMID 39853118, 2025). "Sensitivity of HIV-1 to MX2 activity is affected by complex interactions between CA and cellular proteins involved in the early stages of HIV-1 infection, including nucleoporins (Nups) and the peptidyl-prolyl isomerase cyclophilin A (CypA)." (PMID 38512975, 2024). "In this study, we identify a novel mechanism by which SAMHD1 exerts its inhibitory effect on HIV-1 infection postviral cDNA synthesis through interactions with MX2 and the HIV-1 core protein." (PMID 38888311, 2024). "MX2 inhibits HIV-1 infection prior to the chromosomal integration of proviral DNA, but after the completion of reverse transcription, and current models suggest that it acts by preventing nuclear import of the viral preintegration complex." (PMID 38512975, 2024). "Human myxovirus resistance 2 (MX2/MXB) is an interferon-induced GTPase that inhibits human immunodeficiency virus-1 (HIV-1) infection by preventing nuclear import of the viral preintegration complex." (PMID 38512975, 2024). "Human immunodeficiency virus type-1 (HIV-1) infection is potently inhibited by human myxovirus resistance 2 (MX2/MxB), which binds to the viral capsid and blocks the nuclear import of viral DNA." (PMID 35880880, 2022). "While MX2 depletion increased HIV-1 infection rates in single-round analyses in other cell types between 3- and 11-fold, our results suggest that MX2 is not a relevant HIV-1 restriction factor in resting CD4+ T cells." (PMID 34949807, 2022).
HIV-1 infection (continued). "The results showed that mRNA levels of already known host restriction factors which inhibit HIV-1 infection, TRIM5α, MX2, SAMHD1, SERINC3, SERINC5, IFITM2, IFITM3, ApoE, and PSGL-1 were not significantly elevated by γ-IFN." (PMID 35883685, 2022). "It should be also noted that the consequence of MX2 binding to the capsid is likely more complicated than currently appreciated, as it was shown that MX2 can not only block HIV-1 infection but can also enhance it, depending on its CA sequences." (PMID 34702294, 2021). "Constitutively expressed ISGs regulated by U-ISGF3 included antiviral genes such as BST2, APOBEC3G, MX2 that remained elevated during chronic HIV-1 infection." (PMID 33064743, 2020). "MX2 depletion partially increases HIV-1 infection and is synergistic with inhibition of CypA binding." (PMID 32934084, 2020). "While the precise mechanism of MX2 inhibition of HIV-1 infection remains to be determined, the viral capsid is a critical target of MX2 restriction, since capsid-specific replacement mutations can escape MX2-mediated inhibition." (PMID 33322320, 2020). "MX2 reexpression reduced the infectivity of eGFP-encoding HIV-1LTR to the levels observed in wild-type cells, confirming that MX2 plays a key role in limiting HIV-1 infection in pteropid cells." (PMID 32934084, 2020). "They found that persistent HIV-1 infection in humanized-mice led to induction of IFNs and ISGs including MX2, IFITM3, Trim22, ISG15, OAS1, and IFN regulatory factor 7 (IRF7) both in peripheral blood mononuclear cells (PBMCs) and in the spleen." (PMID 30665429, 2019). "Human myxovirus resistance 2 (MX2/MXB) is an interferon-induced post-entry inhibitor of human immunodeficiency virus type-1 (HIV-1) infection." (PMID 30496303, 2018). "MX2 inhibits HIV-1 infection after the completion of reverse transcription but prior to the chromosomal integration of viral DNA." (PMID 30084827, 2018). "The microarray analysis also showed that HIV-1 infection induced various IFN-stimulated genes (ISGs) including HIV-1 restriction factors such as MX2, APOBEC3G (A3G), BST2, and IFITMs in MDMs." (PMID 30496280, 2018). "MX2 imposes a barrier to HIV-1 infection that follows reverse transcription but precedes nuclear import of the viral cDNA." (PMID 30496303, 2018). "These include host restriction factors such as APOBEC3G, TRIM5α, Tetherin (also known as BST-2), SAMHD1, and MX2, which have been reported to restrict HIV-1 infection and replication." (PMID 30496280, 2018). "Depletion of a number of nucleoporins increased HIV-1 infection in MX2 expressing cells, indicating partial relief from MX2-mediated inhibition (we were unable to deplete NUPL2 using the siRNA pool tested)." (PMID 30496303, 2018). "MX2 has previously been proposed to suppress HIV-1 infection by inhibiting the nuclear import of viral replication complexes, a view supported by the NE localization of the active 78 kDa isoform of MX2." (PMID 30496303, 2018). "Overall, both HIV-1 infection and MX2 activity were affected by Nup perturbation, and these effects were clearly cell-type and cell-cycle dependent." (PMID 30084827, 2018). "In any case, variation in Nup levels has the potential to affect HIV-1 infection and its modulation by cell-cycle, CypA, and MX2." (PMID 30084827, 2018). "We next examined effects of MX2, cell cycle arrest, and CypA/CsA on HIV-1 infection using CA mutants with reported alterations in MX2 and CypA/CsA sensitivity." (PMID 30084827, 2018). "We next sought to determine the importance of Nups and NTRs on HIV-1 infection and the antiviral activity of MX2 in variable cell contexts." (PMID 30084827, 2018). "In contrast to the striking effects on MX2 activity, manipulation of the Nup62 complex had only modest effects on CypA/CsA modulation of HIV-1 infection." (PMID 30084827, 2018). "Here, we reveal that components of the nuclear pore complex, and nuclear import machinery, are required for MX2-dependent inhibition of HIV-1 infection." (PMID 30496303, 2018).